SPATA6 (spermatogenesis associated 6)
Description:
Required for formation of the sperm connecting piece during spermiogenesis. Sperm connecting piece is essential for linking the developing flagellum to the head during late spermiogenesis. May be involved in myosin-based microfilament transport through interaction with myosin subunits.
Synonyms: SRF1; FLJ10007; SRF-1; HASH
Tractability: Antibody: UniProt places it where antibodies can reach, with medium confidence; UniProt predicts a signal peptide or a membrane-spanning region; its Gene Ontology location is reachable by antibodies, with medium confidence. PROTAC: UniProt records ubiquitination sites on it.
Gene: Protein-coding gene on chromosome 1 (48,295,373 to 48,472,279, reverse strand). Ensembl gene ENSG00000132122.
Subcellular location: Secreted; Cell projection, cilium, flagellum
Subcellular location (Human Protein Atlas): Golgi apparatus; Vesicles; Nucleoplasm
Gene Ontology:
Molecular function: protein binding; myosin light chain binding
Biological process: motile cilium assembly; spermatogenesis
Cellular component: sperm head-tail coupling apparatus; extracellular region; motile cilium
Genetic constraint (gnomAD): Loss-of-function variants: 41 observed, 48.46 expected, observed/expected ratio (o/e) 0.85, 90% interval 0.66 to 1.1. The upper end of that interval is the gene's LOEUF score, 1.1, which puts it in group 4 of 6, group 1 being the genes least tolerant of losing a copy. Missense variants: 514 observed, 530.45 expected, observed/expected ratio (o/e) 0.97, 90% interval 0.9 to 1.04. Synonymous variants: 184 observed, 190.18 expected, observed/expected ratio (o/e) 0.97, 90% interval 0.86 to 1.09.
Homologues: Orthologues: macaque SPATA6 (98% identical), chimpanzee SPATA6 (97% identical), dog SPATA6 (94% identical), pig SPATA6 (92% identical), mouse Spata6 (91% identical), rat Spata6 (80% identical), rabbit SPATA6 (78% identical), Drosophila melanogaster CG14079 (12% identical). Paralogues in human: SPATA6L (25% identical).
Diseases named in the same sentence as SPATA6 in open-access papers:
SPATA6 is named in the same sentence as 13 diseases in open-access papers, as found by Europe PMC text mining. Sharing a sentence is not in itself a finding about the gene and the disease. The quoted sentences say what the papers report.
teratozoospermia (2 papers, 2016 to 2021). "Several studies have shown that protein 4.1, SPATA46, CRISP2, Spata6 and other genes play important roles in the process of normal spermatogenesis and have potential as molecular markers for clinical diagnosis of teratozoospermia." (PMID 33819193, 2021).
testicular cancer (2 papers, 2018 to 2021). A primary or metastatic malignant neoplasm that affects the testis. "The expression of spermatogenesis-associated 6 (SPATA6) is significantly elevated in testicular cancer, and inhibition of SPATA6 expression can cause cancer cells to die." (PMID 33728331, 2021). "SPATA6 is involved in sperm formation and development of testicular cancer." (PMID 30349810, 2018).
Infertility (1 paper, 2022). "Investigations in male mice have found that loss-of-function mutations in genes involved in the production of headless spermatozoa, such as Spata6, Hook1, Prss21, Oaz3, and Odf1, can cause fertility reduction or infertility." (PMID 36028792, 2022).
lipoma (1 paper, 2023). A benign, usually painless, well-circumscribed lipomatous tumor composed of adipose tissue. "The GWAS also identified a SNP in LIM domain containing preferred translocation partner in lipoma gene (LPP) and a SNP in spermatogenesis associated 6 gene (SPATA6); both were associated with a 1.64-fold increased odds of early sPTB." (PMID 37450251, 2023).
male infertility (1 paper, 2024). The inability of the male to effect fertilization of an ovum after a specified period of unprotected intercourse. "BAG5-deficient male mice show abnormal assembly of HTCA, leading to ASS and male infertility, phenocopying SPATA6-deficient mice." (PMID 38454159, 2024).
sterility (1 paper, 2024). "For instance, the inactivation of Spermatogenesis-associated 6 (SPATA6) may lead to sterility, while its overexpression has been shown to induce the secretion of testosterone hormone." (PMID 38505001, 2024).
testicular germ cell tumours (1 paper, 2023). "Spata6 is thought to play a key role in testicular germ cell tumours (TGCTs)." (PMID 37398910, 2023).
cancer (3 papers, 2019 to 2021). A tumor composed of atypical neoplastic, often pleomorphic cells that invade other tissues. "The core CT genes include CMTM1, CT83 (CXorf61), EZHIP (CXorf67), DCAF4L2, KHDRBS3, LEMD1, PIWIL1, and SPATA6, which contribute to cancer progression and metastasis." (PMID 33426787, 2021).
tumor (3 papers, 2007 to 2019). "circ_000334, circ_006740, and circ_006371 are spliced from spermatogenesis-associated protein 6 (SPATA6), CUL3, and SLC38A1, which play an important role in tumor proliferation, migration, and apoptosis." (PMID 30349810, 2018).
SPATA6 also shares sentences with these, for which no sentence is quoted: Globozoospermia (1 paper); infection (1); prostate carcinoma (1); type 1 diabetes mellitus (1).